ANO1 (anoctamin 1)
Description:
Calcium-activated chloride channel (CaCC). Plays a role in transepithelial anion transport and smooth muscle contraction. Required for the normal functioning of the interstitial cells of Cajal (ICCs) which generate electrical pacemaker activity in gastrointestinal smooth muscles. Acts as a major contributor to basal and stimulated chloride conductance in airway epithelial cells and plays an important role in tracheal cartilage development. Required for CFTR activation by enhancing endoplasmic reticulum Ca(2+) store release and is also required for CFTR membrane expression. Required for basal and ATP-dependent mucus secretion in airways and intestine, probably by controlling exocytosis of mucus-filled granules by providing Ca(2+) to an apical signaling compartment (By similarity). Contributes to airway mucus expression induced by interleukins IL3 and IL8 and by the asthma-associated protein CLCA1 and is required for expression of mucin MUC5AC. However, was shown in another study not to be required for MUC5AC expression. Plays a role in the propagation of Ca(2+) waves in Kolliker's organ in the cochlea and contributes to the refinement of auditory brainstem circuitries prior to hearing onset (By similarity). In vomeronasal sensory neurons, modulates spontaneous firing patterns in the absence of stimuli as well as the firing pattern of pheromone-evoked activity (By similarity). Responsible for calcium-activated chloride channel activity in type I taste cells of the vallate papillae (By similarity). Acts as a heat sensor in nociceptive neurons (By similarity). In dorsal root ganglion neurons, plays a role in mediating non-histaminergic Mas-related G protein-coupled receptor (MRGPR)- dependent itching, acting as a downstream effector of MRGPRs (By similarity). In the developing brain, required for the Ca(2+)-dependent process extension of radial glial cells (By similarity). [Isoform 4]: Calcium-activated chloride channel (CaCC). Contributes to calcium-activated chloride secretion in human sweat gland epithelial cells. Shows increased basal chloride permeability and decreased Ca(2+)-induced chloride permeability. [Isoform 5]: Calcium-activated chloride channel (CaCC). Shows increased sensitivity to intracellular Ca(2+).
Synonyms: DOG1; ORAOV2; TAOS2; TMEM16A; FLJ10261; INDMS; MYMY7
Tractability: Small molecule: an approved drug acts on it; a high-quality ligand is known. Antibody: UniProt places it where antibodies can reach, with high confidence; its Gene Ontology location is reachable by antibodies, with high confidence; UniProt predicts a signal peptide or a membrane-spanning region; the Human Protein Atlas places it where antibodies can reach. PROTAC: ubiquitination databases record sites on it; its protein half-life has been measured; a small molecule that binds it is known.
Target class: Ion channel; Chloride channel; Other ion channel; Calcium-activated chloride channel
Gene: Protein-coding gene on chromosome 11 (69,985,907 to 70,189,530, forward strand). Ensembl gene ENSG00000131620.
Subcellular location: Apical cell membrane; Presynapse
Subcellular location (Human Protein Atlas): Plasma membrane; Nucleoplasm
Pathways (Reactome):
Disease: Induction of Cell-Cell Fusion
Transport of small molecules: Stimuli-sensing channels
Gene Ontology:
Molecular function: calcium-activated cation channel activity; chloride channel activity; identical protein binding; intracellularly calcium-gated chloride channel activity; iodide transmembrane transporter activity; protein binding; protein homodimerization activity; voltage-gated chloride channel activity; protein dimerization activity; signaling receptor binding
Biological process: chloride transmembrane transport; chloride transport; iodide transport; mucus secretion; protein localization to membrane; cellular response to heat; detection of temperature stimulus involved in sensory perception of pain; glial cell projection elongation; monoatomic ion transmembrane transport; phospholipase C-activating G protein-coupled receptor signaling pathway; cellular response to peptide; monoatomic cation transmembrane transport; trachea development
Cellular component: apical plasma membrane; extracellular exosome; plasma membrane; presynapse; external side of plasma membrane; glutamatergic synapse; presynaptic membrane
Genetic constraint (gnomAD): Loss-of-function variants: 59 observed, 118.52 expected, observed/expected ratio (o/e) 0.5, 90% interval 0.4 to 0.62. The upper end of that interval is the gene's LOEUF score, 0.62, which puts it in group 2 of 6, group 1 being the genes least tolerant of losing a copy. Missense variants: 1,059 observed, 1,299.7 expected, observed/expected ratio (o/e) 0.81, 90% interval 0.77 to 0.86. Synonymous variants: 529 observed, 524.48 expected, observed/expected ratio (o/e) 1.01, 90% interval 0.94 to 1.08.
Homologues: Orthologues: chimpanzee ANO1 (99% identical), macaque ANO1 (98% identical), dog ANO1 (93% identical), rat Ano1 (92% identical), mouse Ano1 (91% identical), guinea pig ANO1 (90% identical), pig ANO1 (88% identical), tropical clawed frog ano1 (80% identical), zebrafish ano1a (59% identical). Paralogues in human: ANO2 (57% identical), ANO4 (39% identical), ANO3 (37% identical), ANO5 (35% identical), ANO6 (34% identical), ANO7 (33% identical), ANO9 (26% identical), ANO8 (19% identical), ANO10 (16% identical), PPP1R7 (9% identical).
Diseases named in the same sentence as ANO1 in open-access papers:
ANO1 is named in the same sentence as 310 diseases in open-access papers, as found by Europe PMC text mining. Sharing a sentence is not in itself a finding about the gene and the disease. The quoted sentences say what the papers report.
gastrointestinal stromal tumor (108 papers, 2012 to 2026). "ANO1 is also closely associated with various other tumors, including gastrointestinal stromal tumors (GIST), esophageal squamous cell carcinoma (ESCC), and pancreatic ductal adenocarcinoma (PDAC)." (PMID 40356890, 2025). "In clinical oncology, the expression of ANO1/DOG1 was considered to have diagnostic specificity for determining which tumor is gastrointestinal stromal tumor to consider targeted therapy." (PMID 29416639, 2018). "The expression of ANO1 is considered to have diagnostic specificity for gastrointestinal stromal tumors." (PMID 29416639, 2018). "Furthermore, global DNA hypermethylation seen in gastrointestinal stromal tumor (GIST) patients leads to recurrent loss of CTCF binding in the boundary between ANO1 and the FGF genes, and higher levels of FGF activity." (PMID 39372737, 2024). "The anoctamin 1 (ANO1/TMEM16A) protein (also known as DOG1) is a marker protein for gastrointestinal stromal tumors, and its role in cell proliferation and development of different types of malignant tumors has been extensively reported." (PMID 38130953, 2023). "A calcium-dependent chloride channel protein called Discovered On Gastrointestinal stromal tumors 1 (DOG1) or anoctamin 1 (ANO1) has a strong impact on IGFBP5 expression in gastrointestinal stromal tumor cell lines." (PMID 36093095, 2022). "For example, anoctamin 1 is particularly expressed in gastrointestinal stromal tumors and head and neck squamous cell carcinomas, where it contributes to cell proliferation, poor prognosis, and metastasis." (PMID 33628598, 2021). "ANO1 is amplified in various types of human malignant tumors, such as head and neck, parathyroid, and gastrointestinal stromal tumors, as well as in breast, lung, and prostate cancers." (PMID 33172169, 2020). "The gene known as anoctamin-1 (ANO-1), also known as discovered on GIST-1 (DOG1), was originally distinguished in gastrointestinal stromal tumors (GIST-1)." (PMID 32692399, 2020). "Before the discovery of Ano1 as a CaCC, Ano1 has been found to be overexpressed in many cancers including gastrointestinal stromal tumor, esophageal squamous cell cancer, and head and neck squamous cell carcinoma (HNSCC)." (PMID 29156699, 2017). "Recently, Ano1, which was first found in gastrointestinal stromal tumour (GIST) and functions as a calcium-activated chloride channel, has been identified as a novel ICC marker in gastrointestine." (PMID 28203258, 2017). "Since the FLJ10261 gene was found to be uniformly expressed with a high level of gastrointestinal stromal tumors (GISTs) thereby being named DOG1 (discovered on GIST1), ANO1/DOG1 has been emerging as a potential diagnostic marker for GIST." (PMID 26811235, 2016). "ANO1, also named DOG1, has been shown to be ubiquitously expressed in gastrointestinal stromal tumors and its overexpression is correlated with development of distant metastases in head and neck squamous cell carcinoma." (PMID 23372686, 2013). "Crofelemer was also found to strongly inhibit the intestinal calcium-activated chloride channel TMEM16A, also known as ANO1 and DOG (anoctamin 1 and Discover On Gastrointestinal Stromal Tumors) by a voltage-independent inhibition mechanism, with a maximum inhibition of 90% and an IC50 of 6.5 μM." (PMID 38265977, 2024). "ANO1 is an established biomarker for gastrointestinal stromal tumors (GIST)." (PMID 33803266, 2021). "‘Discovered on GIST-1’ (DOG1), also known as anoctamin-1 (ANO1), is a calcium-activated chloride channel named for its expression in gastrointestinal stromal tumor (GIST)." (PMID 33921435, 2021). "Amplification or overexpression of ANO1 has been found in several cancers, including gastrointestinal stromal tumor (GIST), head and neck squamous cell carcinoma (HNSCC), prostate cancer, breast cancer and pancreatic cancer." (PMID 27732935, 2016).
gastrointestinal stromal tumor (continued). "It has recently been shown that ANO1/TMEM16A is amplified or overexpressed in several human cancers such as gastrointestinal stromal tumors (GIST), prostate cancer, head and neck squamous cell carcinoma (HNSCC), breast cancer and colorectal cancer cells." (PMID 26305547, 2015). "Ano1 (Dog1) is an established and sensitive marker for the diagnosis of gastrointestinal stromal tumors (GIST) and has recently been identified as a Ca2+ activated Cl− channel." (PMID 22912841, 2012). "ANO1/TMEM16A is highly expressed in several epithelium originated carcinomas, gastrointestinal stromal tumor, esophageal squamous cell carcinoma (ESCC) and pancreatic cancer." (PMID 36033489, 2022). "Before anoctamins (TMEM16 proteins) were identified as a family of Ca2+-activated chloride channels and phospholipid scramblases, the founding member anoctamin 1 (ANO1, TMEM16A) was known as DOG1, a marker protein for gastrointestinal stromal tumors (GIST)." (PMID 30893776, 2019). "Before it was identified as a CaCC in 2008, Ano1 (also known as ORAOV2, DOG1, TAOS2, and FLJ10261) is found to be overexpressed in many cancers such as esophageal squamous cell cancer, gastrointestinal stromal tumor, and head and neck squamous cell carcinoma." (PMID 25961581, 2015). "The coding sequence of ANO1 is located within the 11q13 amplicon, a genomic region that is frequently amplified in various human cancers, such as HNSCC, ESCC, gastrointestinal stromal tumors, and breast and bladder cancer." (PMID 24599954, 2014). "ANO1 is also known as TMEM16A (anoctamin 1, DOG1, ORAOV2, TAOS2, FLJ10261) and is an established biomarker for gastrointestinal stromal tumors (GISTs)." (PMID 22912841, 2012). "ANO1 is also known as DOG1, a marker of gastrointestinal stromal tumors." (PMID 39982585, 2025). "However, with “SIP syncytium,” “ANO1,” “enteric neurons,” “gastrointestinal stromal tumors (GIST),” and “functional dyspepsia (FD),” there has been a growing interest in the relationship between ANO1, SIP syncytium, and ICC, as well as the role of ICC in the treatment of GIST and FD." (PMID 38831987, 2024). "Similarly, anoctamin-1 (ANO1, TMEM16A), a Ca2+-activated Cl− channel serves as tumor marker in gastrointestinal stromal tumor-derived CTCs." (PMID 27618016, 2016). "In gastrointestinal stromal tumors, the expression of ANO1 was significantly negatively correlated with infiltration of plasma cells and memory-activating CD4-positive T cells, suggesting that ANO1 may be participate in the functional suppression of T cells." (PMID 38352864, 2024). "However, its function as a calcium-activated chloride channel suggests that the expression of ANO1 is not restricted to gastrointestinal stromal tumors." (PMID 29416639, 2018). "After identification of ANO1 as Ca2+ activated Cl− channel, it became clear that the protein is identical to DOG1, a significant and reliable tumor marker in gastrointestinal stromal tumors (GIST) and head and neck cancers." (PMID 30893776, 2019). "ANO1 is amplified and highly expressed in a large subset of HNSCC tumors, as well as in a variety of other carcinomas including breast cancer, prostate carcinoma, glioblastoma, GIST (gastrointestinal stromal tumor) and ESCC (esophageal squamous cell carcinoma)." (PMID 25823819, 2015). "Before it was recognized as a CaCC channel, ANO1 was found to be amplified as part of human chromosome 11q13 amplicon in cancers such as esophageal squamous cell cancer (ESCC), gastrointestinal stromal tumor (GIST), head and neck squamous cell carcinoma (HNSCC), pancreatic and breast cancers 26–29." (PMID 24639373, 2014).
breast cancer (68 papers, 2013 to 2025). A primary or metastatic malignant neoplasm involving the breast. "In breast cancer patients treated with tamoxifen, overexpression of the selective estrogen-receptor modulator, Ano1 is associated with good prognosis in PR-positive patients." (PMID 30813939, 2019). "We performed Spearman’s rank correlation coefficient analysis to analyze the association between the expression of Ano1 and Ki67 in breast cancer patients." (PMID 29156699, 2017). "We have previously reported that Ano1 overexpression is associated with good prognosis in PR-positive or HER2-negative breast cancer patients following tamoxifen treatment." (PMID 29156699, 2017). "The high expression of Ano1 was associated with a tendency toward a longer OS in breast cancer with the low expression of Ki67 (P= 0.052), especially in ER-positive (P=0.027), PR-positive (P=0.024), or HER2-negative (P=0.006) breast cancer." (PMID 29156699, 2017). "Our findings suggest the PR and HER2 status can define a subtype of breast cancer in which Ano1 overexpression is associated with good prognosis in patients receiving tamoxifen treatment." (PMID 25961581, 2015). "The high expression of Ano1 was associated with longer OS in patients with PR-positive (p = 0.025) or HER2-negative (p = 0.017) breast cancer." (PMID 25961581, 2015). "The PR and HER2 status defines a subtype of breast cancer in which Ano1 overexpression is associated with good prognosis following tamoxifen treatment." (PMID 25961581, 2015). "We then investigated the association between the Ano1 expression and clinicopathological characteristics of breast cancer." (PMID 25961581, 2015). "The high expression of Ano1 was associated with a tendency toward longer OS in breast cancer patients (n = 395, p = 0.086)." (PMID 25961581, 2015). "We then investigated the association between Ano1 expression levels and therapeutic responses in breast cancer patients receiving chemotherapy and endocrine therapy." (PMID 25961581, 2015). "Ano1 was significantly more associated with breast cancer with the lower clinical stage (stage I or II), or triple-negative status." (PMID 25961581, 2015). "In the present study, we found that overexpression of Ano1 proteins was associated with good prognosis in breast cancer patients following tamoxifen treatment, especially those with PR-positive or HER2-negative status." (PMID 25961581, 2015). "However, we can not exclude the possibility that 11q13 amplification plays a role in Ano1 overexpression in PR-positive tumors, since 11q13 has been identified as a susceptibility locus for ER- and PR-positive breast cancer." (PMID 25961581, 2015). "It is unclear whether Ano1 is associated with clinical outcomes in breast cancer patients with different ER, PR and HER2 status." (PMID 25961581, 2015). "However, the expression level of the Ano1 gene has been found to be associated with poor prognosis in breast cancer patients." (PMID 25961581, 2015). "Additionally, ANO1 expression is closely associated with immunohistochemical markers such as β-catenin, cyclin D1, and E-cadherin, and has been identified as an independent prognostic marker in breast cancer." (PMID 40356890, 2025). "ANO1 dysfunction has been strongly implicated in several pathological conditions, including asthma and hypertension, and has been shown to promote tumor cell proliferation and metastasis in various malignancies, including head and neck squamous cell carcinoma, breast cancer, and gastric cancer." (PMID 40356890, 2025). "In breast cancer, ANO1 inhibition suppresses EGFR phosphorylation, reduces the activity of downstream signaling molecules such as AKT and ERK, and diminishes the autocrine secretion of EGFR ligands, including EGF and transforming growth factor α." (PMID 40356890, 2025). "Inhibition of ANO1 induces G0/G1 cell cycle arrest and significantly reduces the invasiveness of breast cancer cells." (PMID 40356890, 2025).